ERCC6 (ERCC excision repair 6, chromatin remodeling factor)
Diseases named in the same sentence as ERCC6 in open-access papers (continued):
Sharing a sentence is not in itself a finding about the gene and the disease.
COFS syndrome (2 papers, 2019 to 2021). Cerebrooculofacioskeletal (COFS) syndrome is a rare genetic disorder, belonging to a family of diseases of DNA repair, characterized by a severe sensorineural involvement. "At the moment, four different genes are known to cause COFS syndrome: ERCC6 (COFS1, MIM #214150), ERCC2 (COFS2, MIM #610756), ERCC5 (COFS3, MIM #616570), and ERCC1 (COFS4, MIM #610758)." (PMID 33766032, 2021). "Due to the prenatal findings, a COFS syndrome was suspected and further genetic investigation focusing on responsible genes were carried out: ERCC5, ERCC6 and FKTN genes (candidate genes included in the ILLUMINA Trusightone Clinical Exome Sequencing panel)." (PMID 33766032, 2021). "In the first case the COFS syndrome remained undiagnosed, while in the second case, due to prenatal findings of arthrogryposis and cataract, genetic investigation focusing on responsible genes of COFS (ERCC5, ERCC6 and FKTN genes) was carried out." (PMID 33766032, 2021).
glioma (2 papers, 2014 to 2021). A benign or malignant brain and spinal cord tumor that arises from glial cells (astrocytes, oligodendrocytes, ependymal cells). "In total 148 genes are located on 10q25.2-qter, including MGMT, DMBT1 and ERCC6, while the usual suspect, PTEN, is located more proximal to the centromere and is preferentially lost in higher grade gliomas." (PMID 25245118, 2014).
neutropenia (2 papers, 2017 to 2021). A decrease in the number of neutrophils found in the blood. "In our study, we found that rs4253002 in ERCC6 showed significant association with gastrointestinal toxicity in the patients receiving TP regimen, and rs4253212 in ERCC6 showed significant association with neutropenia in the patients receiving GP regimen." (PMID 28924235, 2017). "In subgroup of patients receiving GP regimen, rs4253212 (χ2 test P = 4.92 × 10−5; OR = 3.31, 95%CI:1.26–8.72, P = 0.015) in ERCC6 was significantly associated with neutropenia." (PMID 28924235, 2017). "Polymorphisms in ERCC2, ERCC6, DDB2, RPA1, POLD1 and POLD3 presented significant association with neutropenia." (PMID 28924235, 2017).
oral cancer (2 papers, 2013 to 2022). "SNPs in all eight major NER genes have been implicated in increasing background risk of oral leukoplakia, and altered PBL expression of ERCC1, ERCC5, ERCC6/CSB, and ERCC4 have been found to be higher in patients with oral cancer." (PMID 24364026, 2013).
pancreatic cancer (2 papers, 2018 to 2021). "In this study, we demonstrated that the A alleles of rs2228528 in ERCC6 were significantly associated with longer PFS in pancreatic cancer patients who received FOLFIRINOX chemotherapy." (PMID 33801891, 2021). "In conclusion, we found a novel variant in ERCC6 associated with improved PFS in pancreatic cancer patients who underwent FOLFIRINOX chemotherapy." (PMID 33801891, 2021). "Considering this high VAF, rs2228528 in ERCC6 is a good candidate for a biomarker to predict FOLFIRINOX responses, and is expected to be an especially useful biomarker among Asian pancreatic cancer patients with low BRCA mutation frequency." (PMID 33801891, 2021). "If validated through future large-scale studies, rs2228528 in ERCC6 could be used as a valuable biomarker to help determine whether to use FOLFIRINOX as the first-line therapy in pancreatic cancer patients." (PMID 33801891, 2021). "This study suggests that rs2228528 in ERCC6 could be a potential predictor of response to FOLFIRINOX chemotherapy in patients with pancreatic cancer." (PMID 33801891, 2021). "In this regard, sustained inhibition of the critical DNA repair regulator ERCC6 may be one of the key mechanisms contributing to the anticancer efficacy of FL118 in the drug-resistant pancreatic cancer." (PMID 30285798, 2018). "Furthermore, poly(adenosine diphosphate-ribose) polymerase (PARP) inhibitors are also known to elicit a good response in pancreatic cancer patients with DDR gene mutations, so future studies are needed to determine whether ERCC6 mutations play a role in the response to PARP inhibitors." (PMID 33801891, 2021). "It is unclear whether rs2228528 in ERCC6 directly affects the progression of pancreatic cancer regardless of chemotherapy." (PMID 33801891, 2021). "Similarly, it can be assumed that the rs2228528 in ERCC6 itself does not affect the progression of pancreatic cancer." (PMID 33801891, 2021).
sarcoma (2 papers, 2021 to 2025). A usually aggressive malignant neoplasm of the soft tissue or bone. "The correlation between ERCC6 and HNRNPM was analyzed using four public databases (including osteosarcoma in TARGET, sarcoma in TCGA, GSE21257, and GSE218035), and the results showed a positive correlation." (PMID 40476445, 2025).
astrocytoma (1 paper, 2021). "A patient with an IDH-mutant grade 4 astrocytoma (CL0301) was found to have a germline mutation in ERCC6, an important gene in the DNA double-stranded breaks (DSBs) repair pathway." (PMID 34885201, 2021).
Ataxia (1 paper, 2024). Ataxia refers to impaired coordination of voluntary muscle movement. "The next-generation sequencing panel targeted for ataxia genes evidenced ERCC6 variants, in the absence of other systemic signs suggestive of CS, as shown by the low diagnostic scores (clinical 0/20; clinical–radiological 3/39) and high severity score (14/15)." (PMID 38674442, 2024).
Cachexia (1 paper, 2020). Severe weight loss, wasting of muscle, loss of appetite, and general debility related to a chronic disease. "Loss of transcription-coupled repair, which occurs with mutations in twofold excision repair of cross-complementing genes (ERCC6 and ERCC8) results in CS, which is characterized by progressive cachexia, severe growth retardation and leukoencephalopathy." (PMID 31752481, 2020).
DNA repair disorder (1 paper, 2023). "The DNA repair disorder of CS is caused by ERCC6 or ERCC8 with a proportion around 1:2." (PMID 37592445, 2023).
gastric diseases (1 paper, 2017). "Besides, protein level analysis were performed to compare ERCC6 and ERCC8 expression in different stages of gastric diseases, and to correlate SNPs jointly with gene expression." (PMID 28562347, 2017). "Furthermore, individual and joint expression of ERCC6 and ERCC8 were also evaluated by immunohistochemistry in different gastric diseases, which have never been reported before." (PMID 28562347, 2017).
Huntington disease (1 paper, 2021). Huntington disease (HD) is a rare neurodegenerative disorder of the central nervous system characterized by unwanted choreatic movements, behavioral and psychiatric disturbances and dementia. "KEGG pathway analysis results further revealed that ERCC6 also functioned in Huntington’s disease and ERCC8 showed significant impacts in ubiquitin mediated proteolysis." (PMID 34316408, 2021).
laryngeal carcinoma (1 paper, 2018). Carcinoma that arises from the laryngeal epithelium. "Carriers of Arg1230Pro at ERCC6 had a decreased risk for laryngeal cancer, strongest in heavy smokers and high alcohol consumers." (PMID 29912962, 2018).
melanoma (1 paper, 2016). A malignant, usually aggressive tumor composed of atypical, neoplastic melanocytes. "A similar trend was seen in melanoma, within SLX4, POLE, BRCA1, FANCD2, and ERCC6-mutated tumors containing a significantly higher mutational burden than overall melanoma." (PMID 27004405, 2016).
neuroblastoma (1 paper, 2018). Neuroblastoma (NB) is the most common solid, extracranial childhood tumor. "ERCC6-depleted neuroblastoma cells show defects in gene expression programs required for neuronal differential and fail to differentiate and extend neurites." (PMID 30012197, 2018).
Obesity (1 paper, 2025). Accumulation of substantial excess body fat. "It has recently been shown that a mutation in the gene Ercc6 l2 appears to be the best candidate determining the phenotype of obesity and metabolism in a novel congenic strain LH17LNa." (PMID 40722594, 2025).
osteosarcoma (1 paper, 2025). A usually aggressive malignant bone-forming mesenchymal neoplasm, predominantly affecting adolescents and young adults. "Our findings revealed that cisplatin treatment significantly upregulates ERCC6 expression in OSOs, which correlates with the clinicopathological features of osteosarcoma patients." (PMID 40476445, 2025). "Our results demonstrated that ERCC6 knockdown significantly increased cisplatin sensitivity, reduced proliferation, promoted apoptosis, and suppressed tumor growth in both in vitro and in vivo osteosarcoma models." (PMID 40476445, 2025). "This study utilizes patient‐derived osteosarcoma organoids and CRISPR screening to identify ERCC6 and HNRNPM as key mediators of cisplatin resistance via the PI3K/AKT pathway and BAX alternative splicing." (PMID 40476445, 2025). "Functional rescue experiments further validated the significance of this interaction: while full‐length ERCC6 effectively increase the cisplatin IC50 in osteosarcoma cells, the NBD‐truncated mutant failed to do so." (PMID 40476445, 2025).
Primary amenorrhea (1 paper, 2024). "However, proband POI-588 in our study, harboring heterozygous LoF variants in both MGA and ERCC6, presented with primary amenorrhea, further supporting the likelihood that genetic burden may affect severity of phenotypes." (PMID 39545409, 2024).
rectal cancer (1 paper, 2018). A primary or metastatic malignant neoplasm that affects the rectum. "In addition, ERCC5 and ERCC6 showed marginally significant association with recurrence of rectal cancer with a P value of 0.51." (PMID 29568775, 2018).
urothelial carcinoma (1 paper, 2016). A malignant neoplasm derived from the transitional epithelium of the urinary tract (urinary bladder, ureter, urethra, or renal pelvis). "At the same time, the “risky” ERCC6 1097Val allele increased the frequency of urothelial carcinoma recurrences and the XRCC1 399 A/A (Gln/Gln) genotype greatly reduced recurrence free survival of BCG treated patients." (PMID 26649138, 2016).
cancer (28 papers, 2016 to 2026). A tumor composed of atypical neoplastic, often pleomorphic cells that invade other tissues. "GTF2H1 and ERCC6 regulate nucleotide excision repair, and their loss is expected to result in the compromised ability of cells in DNA repair, a hallmark of cancer progression." (PMID 41468516, 2025). "At present, several studies have assessed the association between ERCC6 rs2228526 polymorphism and the risk of cancer." (PMID 35463969, 2022). "In summary, this meta-analysis demonstrated the there was a significant association between ERCC6 rs2228526 polymorphism and cancer risk according to the current published literatures." (PMID 35463969, 2022). "In order to obtain a more accurate association estimate, we conducted a meta-analysis to find the association between ERCC6 rs2228526 polymorphism and the risk of cancer." (PMID 35463969, 2022). "To provide a more accurate estimate on the association, we performed a meta-analysis search of case-control studies on the associations of ERCC6 rs2228526 with susceptibility to cancer." (PMID 35463969, 2022). "This meta-analysis showed a significant association between ERCC6 rs2228526 polymorphism and cancer susceptibility." (PMID 35463969, 2022). "Thirdly, we just used the unadjusted data to assess the association between ERCC6 rs2228526 polymorphism and cancer risk in this meta-analysis." (PMID 35463969, 2022). "The effect summary odds ratio (OR) with 95% confidence intervals (CI) was applied to assay the association between the ERCC6 rs2228526 polymorphism and the risk of cancer." (PMID 35463969, 2022). "Recent studies have reported the association between ERCC6 rs2228526 polymorphism and risks of various cancers." (PMID 35463969, 2022). "Recently, due to the ERCC6 gene played an important role of in the NER pathway, the ERCC6 RS2228526 polymorphism has been studied in a variety of cancers." (PMID 35463969, 2022). "Among them, our algorithm predicts that EHMT2 and ERCC6 have potential LIR motifs (EHMT2: 262WETV265; ERCC6: 1282VEAE1285), which are disrupted by cancer-associated mutations." (PMID 34059679, 2021). "There are several ERCC6 SNPs (Single-nucleotide polymorphism) that have been associated with increased cancer susceptibility or affected the response to chemotherapy." (PMID 33920220, 2021). "To provide a more accurate estimate on the association, we performed a meta-analysis to assess whether ERCC6 rs2228526 polymorphism increases the risk of cancer." (PMID 35463969, 2022). "The polymorphism in the ERCC6 gene may affect DNA repair ability in the general population and lead to genetic susceptibility to cancer." (PMID 35463969, 2022). "This study suggests that the ERCC6 rs2228526 polymorphism may be associated with increased cancer risk." (PMID 35463969, 2022). "In vitro evidence indicated that ERCC6 polymorphisms may alter protein function, and reduced ERCC6 protein levels were associated with increased cancer risk." (PMID 28562347, 2017). "However, the analysis of genetic variations in papillary neoplasms of low malignant potential (PNLMP) as compared with high grade or poorly differentiated cancer revealed some peculiarities concerning ERCC6 Met1097Val and OGG1 Ser326Cys polymorphisms." (PMID 26649138, 2016). "ERCC6 expression is frequently upregulated in cancer cells, favoring cancer cell proliferation while suppressing apoptosis, which has been recognized as a promising actionable target for cancer treatment." (PMID 35392536, 2022). "Excision repair cross-complementing group 6 and 8 (ERCC6 and ERCC8) have been implicated in ailments such as genetic diseases and cancers." (PMID 34316408, 2021). "The ERCC6 gene has been implicated in autosomal dominant POI and in cancer." (PMID 38996041, 2025).
cancer (continued). "When the study which is not consistent with the HWE equilibrium was excluded from this meta-analysis, this association between ERCC6 rs2228526 polymorphism and cancer risk was not alerted." (PMID 35463969, 2022). "These FL118 efficacy results are consistent with our molecular-targeting data showing that FL118 inhibited the expression of multiple antiapoptotic proteins (survivin, Mcl-1, XIAP, cIAP2) and ERCC6, a critical regulator of DNA repair, in treatment-resistant pancreatic stem-like cancer cells." (PMID 30285798, 2018). "In brief, we hypothesized that downregulation of ERCC6 and ERCC8 may result in lower DNA repair capacity, thus elevating cancer susceptibility by allowing unrepaired DNA damage to remain, ultimately leading to carcinogenesis." (PMID 28562347, 2017). "Two other polymorphisms (XPD Lys751Gln and ERCC6 Gly399Asp) showed similar trends, but the differences between T ≥ 2 low grade tumors and T ≥ 2 high grade carcinomas were not statistically confirmed." (PMID 26649138, 2016). "Therefore, we explored the attributes of eRNA target genes in relation to cancer genomic events and found that these genes, such as dedicator of cytokinesis 8 (DOCK8) and excision repair 6 (ERCC6), exhibit a high burden of mutations and amplifications or deletions change." (PMID 38863031, 2024). "We suggested that ERCC6 and ERCC8 downregulation could induce persistent existence of unrepaired DNA lesions, decreased DNA repair capacity and increased cancer susceptibility, and eventually lead to cancer progression." (PMID 34316408, 2021). "Results of these experiments showed that the expression of ERCC6 and ERCC8 had clinical significance in ailments such as genetic diseases and cancers." (PMID 34316408, 2021). "Several studies have reported a relationship between ERCC8/ERCC6 and the pathogenesis of CS; however, the prognosis ability or mRNA expression of ERCC8 in cancer is seldom reported." (PMID 30417012, 2018). "However, it is unclear whether there are interactions among ERCC6 and ERCC8 SNPs, by which it may enhance the risk warning for GC or its precancerous diseases because SNP-SNP interactions could be more valuable than a single SNP in cancer prediction." (PMID 28562347, 2017). "The mutant of ERCC6 gene has been largely investigated in a variety of cancers, but the effect of ERCC polymorphism in different genetic loci and cancers is not same." (PMID 35463969, 2022). "Cancer cells lacking ERCC6 or ERCC8 protein, which are responsible for DNA repair, may exhibit a more malignant and poorly differentiated phenotype." (PMID 34316408, 2021).
tumor (14 papers, 2016 to 2025). "In vivo experiments showed that ERCC6 knockdown significantly inhibited tumor growth in the presence of cisplatin." (PMID 40476445, 2025). "The comparison of the genotype distribution depending on the tumor stages and tumor tissue differentiation revealed lack of differences, except for the ERCC6 Met1097Val polymorphism (rs2228526)." (PMID 26649138, 2016). "Thus, neoplasms of low malignant potential were distinct from others with respect to genotype distribution of both the OGG1 Ser326Cys and the ERCC6 Met1097Val polymorphisms." (PMID 26649138, 2016). "Among them, cell cycle inhibitors, including Smads and CDKNs, were down-regulated while CDKs, CCNs, E2Fs ATM, ATR, ERCC6, MCMs, and BRCA1 were up-regulated, consistent with a tumor-promoting effect." (PMID 39759123, 2025). "Seven genes out of 13 (CCNH, ERCC2, ERCC6, NEIL1, OGG1, RPA1, XPA) had a significantly different expression in tumour versus normal tissue stored in PAXgene Tissue System." (PMID 27383461, 2016). "The ERCC6 variant (c.1670G > A, p.Arg557His) affecting the helicase ATP-binding domain was present in LLS06, whose tumor was MSS, showed low TMB, and no contribution of MMR deficiency-associated ID mutational signatures." (PMID 33809179, 2021). "As for the joint expression of ERCC6/ ERCC8, double positivity was related to small tumor size (P = 0.005), Borrmman I-II stage (P < 0.001), TNM I-II stage (P = 0.001) (P < 0.001 for T stage), Lauren intestinal type (P = 0.014) of GC and negative perineural invasion (P = 0.015)." (PMID 34316408, 2021). "The analysis exhibited that PR-specific hubs were associated with statistically significant pathways such as Wnt SP, transcriptional misregulation in cancer, ERCC6 (CSB), and EHMT2 (G9a) positively regulate rRNA expression, and chromatin modifying enzymes involved in tumor formation and development." (PMID 28892521, 2017). "When adjusting for certain parameters in the Cox multivariate analysis, analyses results of ERCC6 and ERCC8 expression with IHC and RNA-seq data no longer maintained independent predictive power, which may be due to the complexity of tumor progression." (PMID 34316408, 2021).
genetic diseases (2 papers, 2021). "ERCC6, the gene encoding CSB, is mutated in Cockayne syndrome, a genetic disorder in which affected individuals exhibit neuronal, growth, and developmental abnormalities as well as extreme sun sensitivity." (PMID 34116057, 2021).